SNORA56 (small nucleolar RNA, H/ACA box 56)
Synonyms: ACA56
Gene: Small nucleolar RNA gene on chromosome X (154,774,998 to 154,775,126, forward strand). Ensembl gene ENSG00000206693.
Gene Ontology:
Biological process: RNA processing
Cellular component: nucleolus
Homologues: Orthologues: macaque SNORA56 (98% identical).
Diseases named in the same sentence as SNORA56 in open-access papers:
SNORA56 is named in the same sentence as 2 diseases in open-access papers, as found by Europe PMC text mining. Sharing a sentence is not in itself a finding about the gene and the disease.
SNORA56 shares sentences with these, for which no sentence is quoted: cancer (1 paper); colorectal cancer (1).